GFAP (glial fibrillary acidic protein)
Diseases named in the same sentence as GFAP in open-access papers (continued):
Sharing a sentence is not in itself a finding about the gene and the disease.
tumor (continued). "We also found GFAP expression in MB tumor cells, which was significantly higher in the SHH-MB subgroup and appeared to be associated with worse outcomes, such as recurrence or progression." (PMID 40805120, 2025). "We assessed NRP1 expression in tumor-associated microglia/macrophages (TAMs) and endothelial cells, as well as GFAP expression in astrocytes and tumor cells." (PMID 40805120, 2025). "A significantly higher percentage of GFAP-positive tumor cells was found in the SHH-subgroup, especially in cases classified as MBDN and MBEN, compared to the WNT and non-WNT/SHH groups (Kruskal–Wallis, p = 0.02; Dunn’s post hoc test, p = 0.01)." (PMID 40805120, 2025). "The tumour cells and processes had diffuse synaptophysin positivity, and ganglion cells were GFAP positive, suggestive of an anaplastic ganglioglioma." (PMID 40013208, 2025). "Immunohistochemical and immunofluorescence staining showed modulation of intracytoplasmic Ki67, cytoplasmic CMPK2, and GFAP expressions in tumor cells post-BA treatment." (PMID 39821858, 2025). "Immunohistochemical detection of the expression of S-100, SOX10, and GFAP in tumour cells can assist in differential diagnosis." (PMID 41357577, 2025). "The quantity of these GFAP+ cells surrounding tumor cells diminished in the treated cases compared to untreated controls (p = 0.0071)." (PMID 41009470, 2025). "To assess tumor cell proliferation during the treatment, we used the marker of proliferation Kiel 67 (Ki-67) and the glial fibrillary acidic protein (GFAP)." (PMID 41148834, 2025). "GFAP+ cells were observed in two different locations, in the middle of the necrotic areas and in the periphery of these areas, in close relation with tumor cells, suggesting reactive astrocytes." (PMID 41009470, 2025). "The number of GFAP-positive cells in the area of brain damage, in tumor growth zones, and in marginal zones was also extremely low." (PMID 41148834, 2025). "To assess varying levels of GFAP expression in both the tumor and peritumoral regions—as seen in patients—we applied our strategy across three GB mouse models, which themselves exhibit distinct patterns of GFAP expression." (PMID 40842154, 2025). "The successful acquisition of the MMPIbrain was defined as the presence of tumor cells within the gliosis (GFAP-positive area) in the MMPIbrain sample." (PMID 40712433, 2025). "In IHC staining with antibodies to the oligodendrocyte marker protein Olig2 and the mature astrocyte marker GFAP, as well as the stem cell marker Sox2, a large number of Olig2+ and Sox2+ cells were observed in the tumor node relative to the peritumoral zone." (PMID 41009560, 2025). "Normal organoids provided not only a larger surface for tumor-like cells to spread but also extended GFAP-positive astrocytic protrusions into the sphere." (PMID 40917877, 2025). "The co-localization of NMBR and GFAP were observed in tumor-invading sites of sciatic nerve, with a Pearson’s colocalization coefficient of 0.41 and 0.81 in Hela and ME180 PNI models, presenting that NMBR is located in activated Schwann cells." (PMID 39214988, 2024). "Tumor cells were positive for Olig2 and GFAP, while immunohistochemical staining for neuronal markers was negative." (PMID 38902810, 2024). "Chromogenic and fluorescent IHC (GFAP, CD45 and EGFR).Further characterisation of CTC and associated tumour: comparative genomic hybridization, sequence analysis and FISH." (PMID 38481938, 2024). "While these tumor cells express S-100 and vimentin, their reactivity to glial fibrillary acidic protein is variable." (PMID 39070413, 2024). "The macro images of GFAP immunoreactivity showed higher fluorescence intensity in the tumour than in the muscle." (PMID 39065752, 2024). "Tumour cells demonstrated strong positivity for glial fibrillary acidic protein (GFAP) and were also positive for OLIG2." (PMID 39441398, 2024).
tumor (continued). "Our histological analysis further supports this idea by confirming the presence of GFAP-positive astrocytes and Cx43 at the tumor border." (PMID 38489314, 2024). "On immune labelling, the tumor cells reacted partially positive for the glial fibrillary acidic protein (GFAP) and, less frequently, the oligodendrocyte transcription factor Olig2 (not shown)." (PMID 38345610, 2024). "Gli-55 aptamer demonstrated good binding to tumor cells but was found to bind to glial fibrillary acidic protein (GFAP)." (PMID 39682297, 2024). "Despite this variation for GFAP and synaptophysin staining, desmin was positive in a significant percentage of neoplastic cells throughout the neoplasm, with rare cells showing densely eosinophilic cytoplasm or elongation." (PMID 39228008, 2024). "Most of the tumor cells were positive for the glial fibrillary acidic protein (GFAP), CD34 (diffuse cytoplasmic and membranous positivity), with focal expression of Neu-N and synaptophysin on immunohistochemical analysis (IHC)." (PMID 39409964, 2024). "The immunophenotype is quite characteristic as this tumor exhibits a diffuse positivity for S100, a variable expression of GFAP, and neuronal markers." (PMID 38544524, 2024). "In our case, both S100 and GFAP are positive, with a Ki-67 index of 3%-4%, indicating a low-grade tumor." (PMID 39295729, 2024). "One population is that of macrophages or microglia, which have phagocytosed GFAP-expressing cells or debris in the tumor tissue sample from astrocytes or tumor cells)." (PMID 38295184, 2024). "Glial fibrillary acidic protein (GFAP) loss indicates malignancy and characteristic undifferentiated tumor cells." (PMID 38523646, 2024). "Lastly, we looked at GFAP as a marker of tumour cells, finding that GFAP-positive cells were incorporated into all patients with available tissue sections for this marker." (PMID 39724753, 2024). "The tumor was diffusely positive for glial markers (GFAP and OLIG2) and there was widespread expression of synaptophysin." (PMID 38650040, 2024). "Statistical analysis revealed that nearly half of the GFAP-positive astrocytes were within the tumor, with 63.9% being located near the tumor surface (±200 μm)." (PMID 38775133, 2024). "Tumor cells showed regional immunohistochemical positivity for glial markers as Olig2 and GFAP, MIB-1 (Ki-67) proliferation index exceeded 25%." (PMID 38902810, 2024). "Overall analysis of endothelial-enriched markers revealed gaps in the tumour vasculature ranging from 60.0 %-87.5 % of all cases, while GFAP staining was only available in 7 patients and was detected in the tumour vasculature of all patients." (PMID 39724753, 2024). "The tumour-to-muscle ratio of the analysed fluorescence intensity in the images of GFAP-positive cells correlated well with the [111In]In-DOTA-Ahx-R954 accumulation." (PMID 39065752, 2024). "Some tumour case series showed ependymoma-like features, with demarcated morphology, monomorphism, and perivascular pseudorosettes, highlighted with GFAP." (PMID 39126064, 2024). "Immunohistochemical staining for GFAP showed that 13 of the tumor tissues were considered positive (21.31%, 13/61), but it did not affect PFS (p = 0.546)." (PMID 39066950, 2024). "To understand the role of C3 and complement in the tumor microenvironment, we returned to stain the murine GBMs for C3, GFAP, Olig2, and Nestin to highlight perivascular tumor areas." (PMID 39172519, 2024). "Following ON-CR at 6 weeks of age, Nf1OPG mice exhibit increased optic nerve volumes, tumor proliferation (%Ki67+ cells), cell density and GFAP expression at 12 weeks of age, relative to sham controls." (PMID 38308315, 2024). "Immunohistochemistry can reveal specific markers for this type of tumor, such as S100 protein (+), vimentin (+), and glial fibrillary acidic protein (GFAP) (−), among others." (PMID 39444783, 2024).
tumor (continued). "Other neoplasms that have been reported in patients with GFAP astrocytopathy include head and neck squamous cell carcinoma, pleomorphic parotid adenoma, small-cell carcinoma, and carcinoid." (PMID 39449321, 2024). "The tumor cells were positive for glial markers (GFAP, OLIG2) and markers of neuronal differentiation (synaptophysin, chromogranin) were focally expressed within the tumor." (PMID 38650040, 2024). "A combined GFAP/Ki67 stain showed rare, atypical GFAP-positive proliferating tumor cells in the glial component." (PMID 39707480, 2024). "All of the PAs studied and 96% of the CAs were positive for GFAP with intensely immunopositive tumor cells located at the interface of the tumor with the connective tissue." (PMID 38929710, 2024). "CD11c+ and P2RY12+ cells were the predominant TIM3+ expressing population with minimal TIM3 expression on GFAP+ tumor cells or CD3+ lymphoid cells." (PMID 39137048, 2024). "A histochemical analysis of the tumor tissue revealed the presence of positive glial fibrillary acidic protein (GFAP)." (PMID 39459474, 2024). "CD11b-positive cells were more abundant in GL261-CIITA tumors (55%–60%) compared to GL261 (15%–20%) and mostly localized along the tumor margins, similarly to what we observed for GFAP-positive astrocytes." (PMID 36993983, 2023). "Five studies labelled tissue sections with glial fibrillary acidic protein (GFAP) to identify tumour cells." (PMID 36823554, 2023). "It is possible that ectopic expression of GFAP in the neoplasm triggered the autoimmune response against GFAP including the production of GFAP-specific CD8 + T cells and B cells." (PMID 37016352, 2023). "In fish, GFAP has been used to map glial structures both in the brain and other areas such as the gut, as well as a tumor marker." (PMID 37760333, 2023). "The CTCs observed were: 18 CTCs (tumor astrocytes, GFAP+ and/or EGFR-Ki67+), 86 nucleated hematopoietic (nH) cells (non-tumoral cells, CD45+), 12 double-positive cells (dposCTCs) (GFAP+/CD45+ or EGFR-Ki67+/CD45+), and 158 unstained cells (only Hoechst+)." (PMID 37373295, 2023). "By immunohistochemistry, the tumour strongly expressed S100 and GFAP in addition to intense nestin positivity, while OLIG2 was negative in the perivascular tumour cells." (PMID 37362245, 2023). "We found that GFP-tagged GBM cells invading away from the edge of the tumour spheroid can interact with αSMA-positive vasculature and GFAP-positive astrocytes." (PMID 36793608, 2023). "After the infusion of ECM gels into the scaffold, the tumor cells spread and migrated to fill the pores with dense and extensive Nestin+ and GFAP+ processes." (PMID 37508868, 2023). "The tumor cells demonstrated variable immunoreactivity for the glial fibrillary acidic protein gene (GFAP), neuron-specific enolase (NSE), and CD56." (PMID 36915840, 2023). "In a DE analysis between GFAP+ (Astrocyte/Tumor) and CD45+ (immune) segments using a cutoff of FDR < 0.001 and fold change (FC) >2, we identified 25 proteins and 88 genes that were differentially expressed in a subset of samples." (PMID 37377888, 2023). "Tumor cells were diffusely positive for Synaptophysin, CD56, INI1 and SMARCA4 associated with negativity for GFAP, OLIG-2, EMA, BCOR, LIN28A and MIC-2." (PMID 36934287, 2023). "In pediatric GBM, according to WHO grade IV of this tumor, few GFAP fragments were detected, and vimentin fragments, when present, showed a different distribution between male and female patients, highlighting sexual dimorphism in pediatric GBM disease." (PMID 37761239, 2023). "Both tumor models reveal a high degree of overlap between GFAP (red pseudocolor) and EGFP (green pseudocolor), with minimal overlap between tumor cells (light blue pseudocolor) and EGFP, indicating that EGFP-positive cells are likely astrocytes." (PMID 38014191, 2023). "Tacrolimus (FK506) has capacity to increase chemosensitivity of GSC and reduce GBM tumor volume and hypoxia-induced surface markers (ki67, GFAP and nestin) in GSC." (PMID 37174078, 2023).
tumor (continued). "Using the Lunaphore COMETTM spatial multiplex platform, we further evaluated the immune spatial landscape in 2 GBM patients by staining for B cells (CD20+), T cells (CD8+), myeloid cells (CD163+), epithelial cells (CD31+), tumor cells and astrocytes (GFAP+)." (PMID 38268923, 2023). "In contrast, GFAP+ astrocytes were progressively located closer around the tumor from DoC 24 to DoC 31 and DoC 37 when we followed GPF-GICs-organoids growth." (PMID 37190034, 2023). "A significant progressive increase of GFAP protein expression from DoC 24 to 37 (p < 0.05) surrounding tumor masses concerning the expression on peripheral areas was observed." (PMID 37190034, 2023). "Of these studies, three used GFAP labelling to confirm that cells lining VM vessels were tumour cells." (PMID 36823554, 2023). "It stains positively for GFAP, which was commonly observed in the tumor edge area and also in the vicinity of small vessel walls within the tumor." (PMID 38003507, 2023). "GFAP expressed by neoplasia is plausible as an immunogen-triggering paraneoplastic neurological autoimmunity." (PMID 37016352, 2023). "Histopathological examination revealed a moderately cellular tumor composed of medium-sized multipolar or elongated glial fibrillary acidic protein (GFAP)–positive astrocytes with projections creating a fibrillar background." (PMID 37165121, 2023). "We also immunostained the human GBM tissue with IBA1 and GFAP to assess the distribution of microglia/astrocytes in accordance with GBM tumor." (PMID 37468961, 2023). "Resected tumors were immuno-labeled against glial fibrillary acidic protein (GFAP) to detect astrocytes, another candidate tumor-associated cell population." (PMID 38014191, 2023). "Tumor cells were diffusely positive for Synaptophysin, CD56, INI1, SMARCA4 and ATRX associated with negativity for GFAP, OLIG-2, EMA, BCOR, LIN28A, EZHIP, MIC-2, Cytokeratin’s, SMA, Desmin and Myogenin." (PMID 36934287, 2023). "We found that the relationship between serum GFAP kinetics and tumour growth strongly depends on the tumour." (PMID 35919979, 2022). "The tumor was highly proliferative (Ki-67 index 68.7%) and showed positive glial fibrillary acidic protein and vimentin by immunohistochemistry." (PMID 35278143, 2022). "In 3D-SFs, tumor cells enveloped the scaffold surface consisting of mostly GFAP+ cells and some Nestin+ cells." (PMID 35381525, 2022). "In this model, GFAP-positive tumor cells expressed cre to drive recombination in a cell type-specific manner." (PMID 35446393, 2022). "We also identified weak immunoreactivity of OATP1A2, 2B1 and 1C1 on GFAP+ cells in non-tumor tissue." (PMID 36382105, 2022). "Only blank brain scans were produced when the GFAP PNA alone or the CAV PNA alone were injected intravenously in the tumor-bearing rats." (PMID 35745855, 2022). "GL261-derived tumor cells stained positively for Ki67, while the major presence of GFAP positive cells was found in the periphery of the tumor, which is suggestive of astrogliosis." (PMID 35402232, 2022). "The amount of ACSL4+ cells of the GFAP+ cells increased significantly by an average of 29.3% (p<0.001) between primary and relapsed tumor." (PMID 35530303, 2022). "We investigate current detection limits, show how the serum GFAP levels depend on the tumour characteristics, determine the key parameters which limit detection and explore future strategies." (PMID 35919979, 2022). "As the healthy baseline concentration of GFAP rises the GFAP contribution required from the tumour to reach the detection cut-off threshold drops and therefore the tumour is detected earlier at a smaller volume." (PMID 35919979, 2022). "EGFR and GFAP were predominantly expressed by tumor cells, often at varying levels, with expression of both proteins highest in EGFR-amplified tumors, consistent with the AC-like differentiation of these tumors." (PMID 35973991, 2022).
tumor (continued). "Tumor cells with high sialyl expression and/or positive intracellular GFAP expression yield faster induction of GuaDex toxicity." (PMID 35312943, 2022). "MT2A, TIMP1, and GFAP are more highly expressed in tumor cells and are down-regulated in the periphery." (PMID 35327982, 2022). "The population of tumor-derived astrocytes was identified by the upregulation of canonical astrocytic markers, including GFAP, AQP4, GJA1, and S100B." (PMID 35803925, 2022). "We utilized the pan-myeloid marker, IBA1; pan astrocyte (non-tumor) and tumor cell marker GFAP; endothelial cell marker (UAE-1-lectin); and stromal cell marker PDGFRβ." (PMID 36382105, 2022). "We detected significantly higher KI67 and significantly lower GFAP expression in the Lrig1 KO tumours than WT controls." (PMID 36420140, 2022). "In silico modelling was paired with experimental measurement of cell GFAP concentrations and used to predict the tumour volumes and identify key parameters which limit detection." (PMID 35919979, 2022). "As our understanding, classification and quantification of different GBM types improve, it will be possible to incorporate changes in the GFAP expression with tumour growth for different tumour types into our models." (PMID 35919979, 2022). "in case of WT Pcdh10 (Pcdh10+/+), tumor formation was dependent on GFAP-Cre driven Rb ablation; iii." (PMID 35468745, 2022). "The lung biopsy showed a heterogeneous tumor with diffuse GFAP expression, which exhibited areas of pleomorphic cells embedded in a myxoid extracellular matrix showing brisk mitotic activity and areas of fibroblastic-like cells with lower mitotic activity." (PMID 35932030, 2022). "Fischer CD344 rats bearing an intra-cranial RG-2 tumor were studied for brain imaging with either the CAV PNA or the GFAP PNA." (PMID 35745855, 2022). "This causes a synonymous relationship between tumour volume and serum GFAP, which becomes increasingly heterogenous and, in some cases, lower with tumour growth." (PMID 35919979, 2022). "Despite the large heterogeneity in the timescales involved in the dynamic GFAP concentration profiles (which depend on the characteristics of a specific tumour), for all tumours, the levels of GFAP initially follow the same trend, increasing with volume." (PMID 35919979, 2022). "Tumours are incredibly heterogenous and are represented by a wide range of parameters, which leads to analogously heterogenous detection volumes and dynamic GFAP profiles." (PMID 35919979, 2022). "Heterogeneity and, in some tumours, a decrease in GFAP expression with tumour growth have been observed in astrocytic tumours." (PMID 35919979, 2022). "Comparatively, OATP expression appeared widespread in GBM tissue, with immunoreactivity observed not only on vascular structures, but by IBA1+ cells, and GFAP+ cells throughout the tumor parenchyma." (PMID 36382105, 2022). "Accordingly, we observed that GFAP immunoreactivity was highly upregulated in astrocytes localized at tumor margins, and that GFAP-upregulated astrocytes exhibited a reactive structure (A′)." (PMID 35474103, 2022). "The tumor cells showed positivity in the immunohistochemical reaction for glial fibrillary acidic protein (GFAP)." (PMID 36414742, 2022). "We found that the levels of GFAP in the blood are related to tumour characteristics, such as vasculature damage and rate of necrosis, which are biological markers of tumour aggressiveness." (PMID 35919979, 2022). "We also found a similar expression pattern of CD133 and GFAP markers in small tumors formed under FMOD-silenced conditions in all three tumor models." (PMID 35642785, 2022). "The immunohistochemistry localization due to GFAP staining is performed to identify the malignancy and giant tumor cells." (PMID 35035811, 2022). "Patient-derived surgical specimens were subjected to molecular analysis, which revealed the tissue to be GBM with the tumor cells highly expressing GFAP, Ki67, and IDH1 R132H." (PMID 35646111, 2022).